LINC00612 (long independently transcribed non-coding RNA 612)
Synonyms: C12orf33; MGC40170; FLJ41814
Gene: Long non-coding RNA gene on chromosome 12 (9,055,589 to 9,066,123, reverse strand). Ensembl gene ENSG00000214851.
Diseases named in the same sentence as LINC00612 in open-access papers:
LINC00612 is named in the same sentence as 7 diseases in open-access papers, as found by Europe PMC text mining. Sharing a sentence is not in itself a finding about the gene and the disease. The quoted sentences say what the papers report.
bladder cancer (4 papers, 2019 to 2023). "Miao et reported that LINC00612 acts as ceRNA by sponging miR-590 to enhance the proliferation and invasion of bladder cancer cells." (PMID 34367236, 2021). "In this study, we found that LINC00612 is significantly upregulated in bladder cancer tissues and cell lines." (PMID 30940184, 2019). "In summary, our results suggest that the expression of LINC00612 is elevated in bladder cancer and can promote tumor cell proliferation and invasion in bladder cancer, as confirmed by in vivo and in vitro experiments." (PMID 30940184, 2019). "Further studies confirmed that LINC00612 could promote tumor proliferation and invasion in vivo and in vitro, suggesting that LINC00612 may be a potential target for observation and treatment of bladder cancer." (PMID 30940184, 2019). "LINC00612 may be a novel bladder cancer marker and a potential therapeutic target." (PMID 30940184, 2019).
colon adenocarcinoma (1 paper, 2024). "Briefly, LINC00612 expression levels in colon adenocarcinoma cell lines were examined, and the effects of LINC00612 knockdown on the proliferation and apoptosis of colon adenocarcinoma 5-FU-resistant cells were analyzed." (PMID 38806777, 2024). "Given that lncRNAs adsorb miRNAs to modulate downstream target mRNA, we further explored the LINC00612-mediated molecular mechanism in colon adenocarcinoma progression." (PMID 38806777, 2024). "Mechanistically, LINC00612 specifically bound to miR-590-3p, which promoted 5-FU resistance in colon adenocarcinoma cells and attenuated the inhibitory effect of LINC00612 on GOLPH3 expression." (PMID 38806777, 2024).
colon cancer (1 paper, 2024). "PSB markedly suppressed cell viability and facilitated apoptosis, and inhibition of LINC00612 dramatically further aggravated the effects of PSB on colon cancer cells, whereas elevated LINC00612 expression markedly reversed these effects." (PMID 38806777, 2024). "Furthermore, LINC00612 expression was aberrantly elevated in colon cancer cells compared to that in NCM460 cells." (PMID 38806777, 2024). "In addition, we confirmed that PSB attenuated 5-FU chemoresistance in colon cancer by targeting LINC00612, which may provide a novel treatment strategy for 5-FU chemoresistance in colon cancer." (PMID 38806777, 2024).
osteosarcoma (1 paper, 2021). A usually aggressive malignant bone-forming mesenchymal neoplasm, predominantly affecting adolescents and young adults. "For example, LINC00612 is a ceRNA for miR-214-5p, and it can indirectly up-regulate SOX4 to promote the proliferation, migration, invasion and epithelial-mesenchymal transition of osteosarcoma cells." (PMID 34224294, 2021).
tumor (3 papers, 2019 to 2024). "The results of ISH and RT-RT-qPCR revealed that the expression of LINC00612 was higher in tumor tissues than that in normal tissues." (PMID 30940184, 2019). "In the subcutaneous tumorigenesis experiment of SW620 cells, compared with the sh-NC group, the weight and volume of tumor tissue in the sh-LINC00612 group was significantly reduced, which indicated that the malignant process of the tumor was inhibited after inhibiting the expression of LINC00612." (PMID 38806777, 2024). "However, whether LINC00612 modulates chemoresistance in tumor remains unclear." (PMID 38806777, 2024).
LINC00612 also shares sentences with these, for which no sentence is quoted: cancer (2 papers); Graves disease (1).